S100A8 (S100 calcium binding protein A8)
Diseases named in the same sentence as S100A8 in open-access papers (continued):
Sharing a sentence is not in itself a finding about the gene and the disease.
lung carcinoma (continued). "Taken together, our results indicate that S100A8 favourably modified the cancer microenvironment in the lungs to promote effective immune responses and may represent a new treatment option that complements current therapeutic strategies in lung cancer." (PMID 35655772, 2022). "Our results indicate that treatment with S100A8 may favourably modify the lung microenvironment to promote an effective immune response in lungs, thereby representing a new strategy that could complement current immunotherapies in lung cancer." (PMID 35655772, 2022). "However, it remained to be addressed how an S100A8/A9-NPTNβ signal that led to SPDEF activation might control the upregulation of lung cancer dissemination." (PMID 32490214, 2020). "S100A8 and S100A9 were found increased in inflammatory diseases and cancers including osteosarcoma, lung carcinoma, and cervical cancer." (PMID 39575241, 2024). "Here we made the novel observation that intranasal administration of S100A8 reduced accumulation of PMN-MDSC and M-MDSC in lungs from mice with early-stage lung cancers." (PMID 35655772, 2022). "We observed S100A8+ and S100A9+ myeloid cells infiltrating growing lung cancers at midpoint of survival in the orthotopic LLC lung tumour mouse model; PMN-MDSC were the predominant myeloid subset, as reported by others." (PMID 35655772, 2022). "The clinical examination of plasma S100A8/A9 and HRG levels showed that lung cancer patients with brain metastasis had higher S100A8/A9 and lower HRG levels than nonmetastatic patients." (PMID 36142212, 2022). "Control mice had extensive lung cancers (HBSS: 49.9 ± 10.5 mm2), whereas only small cancer nodules were present in S100A8-treated mice (8.4 ± 4.6 mm2) (p < 0.01)." (PMID 35655772, 2022). "In marked contrast, S100A8 treatment significantly delayed early lung cancer growth with 4 of 7 (57%) mice having no visible lung cancer nodules." (PMID 35655772, 2022). "Finally, to consolidate these in vitro and in vivo findings, we investigated the plasma levels of S100A8/A9 and HRG in clinical patients who suffered from brain metastasis of lung cancer." (PMID 36142212, 2022). "Increasing concentrations of S100A8 did not affect proliferation or viability of mouse or human lung cancer cells in vitro, suggesting that S100A8 likely delayed engraftment of lung cancers by alternate mechanisms." (PMID 35655772, 2022). "Here we show significantly less nitrite levels in bronchoalveolar lavage fluid from mice with lung cancers treated with S100A8, even though iNOS mRNA expression was not altered." (PMID 35655772, 2022). "Moreover, S100A8 can induce the activation of MPO, and novel monoclonal antibody against it efficiently prevents lung cancer metastasis." (PMID 34993203, 2021). "In addition, the EVs isolated from the serum of lung cancer patients also stimulated NK cells to produce VEGF, CXCL1 and S100A8, which contributed to angiogenesis and immune suppression in the TME." (PMID 34944871, 2021). "We also found that NK cells from lung cancer patients had lower expression of CD226 on their surface and exhibited a pro-inflammatory, pro-angiogenic and tumorigenesis phenotype by expressing VEGF, CXCL1, CXCL8, S100A8 and MMPs." (PMID 34944871, 2021). "In breast and lung cancer models, TNF-α has been shown to modulate a chronic inflammatory circuit (TNF-α → CXCL1/2 → MDSC recruitment → S100A8) that disrupts the TME and facilitates chemoresistance and metastasis; interruption at any point in this cascade may markedly reduce tumors’ aggressiveness." (PMID 40430573, 2025). "Given S100A8 inhalation suppressed but did not abolish lung cancer growth, future studies to determine whether other therapeutic drugs could work in combination with S100A8 are warranted." (PMID 35655772, 2022).
lung carcinoma (continued). "In this study, we showed that the growth and viability of mouse and human lung cancer cells treated with S100A8 over 7 days in culture did not change, indicating that S100A8 may regulate tumor growth or spread of different cancers through different mechanisms." (PMID 35655772, 2022). "However, depletion of Arg may not be conducive to effective T cell function, and S100A8 treatment significantly elevated CD3+ T cells numbers in lungs of mice with early-stage lung cancers." (PMID 35655772, 2022). "Immunohistochemical analysis using specific anti-S100A8 and S100A9 antibodies detected S100A8+ and S100A9+ myeloid cells infiltrating lung cancers (8 cells per field of view), but not in lung tumor cells." (PMID 35655772, 2022).
leukemia (24 papers, 2011 to 2026). A malignant (clonal) hematologic disorder, involving hematopoietic stem cells and characterized by the presence of primitive or atypical myeloid or lymphoid cells in the bone marrow and the blood. "Differential gene expression analysis found that many upregulated genes in the C2 subtype were associated with increased leukemia cell survival, proliferation, and drug resistance, such as S100A8, S100A9, LILRB3, KLF4, LST1, and ITGB2." (PMID 37691822, 2023). "The high expression of S100A9 and S100A8, pro-inflammatory proteins, is associated with poor prognosis in patients with different types of cancer, including glioma or leukemia." (PMID 36552040, 2022). "Microarray experiments conducted on leukemia cell lines treated with the bromodomain inhibitor JQ1 showed that JQ1 causes a significant downregulation of S100A8 and S100A9 transcripts in OCI-AML3 cells." (PMID 29955397, 2018). "Although PON demonstrated good results for treating patients with leukemia, it also exhibited severe side effects, including cardiotoxicity; a recent study reported that it caused myocardial and systemic inflammation due to the activation of the S100A8/A9-TLR4-NLPR3-IL-1β signaling pathway." (PMID 39857282, 2025). "The sensitivity of leukemia cells to chemotherapy and apoptosis should be increased through S100A8 silencing, and the potential mechanism is related to the increased intracellular Ca2+ levels and apoptosis induced by endoplasmic reticulum stress." (PMID 38361783, 2024). "Recent studies revealed that S100A8 plays an important role in the apoptosis/proliferation of leukemia cells." (PMID 36180909, 2022). "Because leukemia patients develop resistance to imatinib after prolonged treatment and show severe adverse clinical implications, we investigated the efficacy of S100A8 and S100A9 against imatinib resistance." (PMID 32903598, 2020). "Although TLR4 expression in EoL-1 cells is similar to that in other leukemia cells, EoL-1 cells undergo apoptosis subsequent to S100A8 and S100A9 treatment." (PMID 32903598, 2020). "In leukemia cell lines, it is possible that the expression of S100A8 and S100A9 determines the effect that bromodomain inhibition has on autophagy." (PMID 29955397, 2018). "Daunorubicin has been shown to induce autophagy in leukemia cell lines by activation of the MEK/ERK pathway which in turn induces expression of S100A8 and S100A9 in cancer cells." (PMID 29955397, 2018). "Numerous studies have shown inhibition of S100A8 as a viable treatment strategy for cancers, including leukemia." (PMID 28183295, 2017). "Moreover,apoptosis in these mutant stem cells increased in the inhibitor-treated mice, suggesting that S100a9 and S100a8 played animportant role for the survival of these leukemia initiating cells." (PMID 39149498, 2024). "Biological experiments confirmed that S100a9/S100a8 conferred aselective advantage to the leukemia-initiating cells through autocrine effects andfacilitated immune evasion by recruiting and promoting immune suppressive myeloid-derivedsuppressor cells (MDSCs) in the microenvironment." (PMID 39149498, 2024). "Importantly, pharmacological inhibitionof S100a9/S100a8 signaling effectively impeded leukemia development fromPtpn11E76K/+ mutant stem cells." (PMID 39149498, 2024). "The overexpression of S100a9 and S100a8 byPtpn11E76K/+ mutant stem cells appeared topromote the growth of these leukemia-initiating cells.Ptpn11E76K/+ stem cells cultured inex vivo expansion medium exhibited significantly acceleratedproliferation compared to WT HSCs." (PMID 39149498, 2024). "In drug resistance leukemia cells, chemotherapy agents could induce S100A8 expression and S100A8 elevated." (PMID 36180909, 2022).
leukemia (continued). "In addition, knockdown of S100A8 expression increased the sensitivity of leukemia cells to chemotherapy and apoptosis." (PMID 33801279, 2021). "In DOX-resistant leukemia cells, an increase occurs in expression of P-gp and S100A8." (PMID 33187385, 2020). "Further studies indicated that S100A8 might contribute to drug resistance in leukemia by regulating autophagy." (PMID 25628518, 2015). "Notably, this effect wasblocked by the S100a9/S100a8 inhibitor tasquinimod, indicating that the overproduction ofS100a9 and S100a8 by leukemia-initiating Ptpn11 mutant stem cells maycontribute to the recruitment of MDSCs to the microenvironment." (PMID 39149498, 2024). "Furthermore, administration of theS100a9/S100a8 inhibitor impedes leukemia development fromPtpn11E76K/+ mutant stem cells.These results strongly suggest that the overexpression of S100a9 and S100a8 byPtpn11- mutated stem cells plays a pivotal role in the initialleukemogenic process." (PMID 39149498, 2024). "Recently, some authors have discussed the role of serum cytokines and chemokines, such as S100A8/A9, in differentiating CNO from other conditions such as leukemia, infections, IBD, and healthy control." (PMID 34202154, 2021). "Curcumin (0–32 μM) as a potential antitumor agent, reduces expression of S100A8 and P-gp in a time- and dose-dependent manner to promote DOX accumulation and induce apoptosis in leukemia cells." (PMID 33187385, 2020). "The effects of S100A8 and S100A9 on leukemia are induced by more complex mechanisms beyond our understanding." (PMID 32903598, 2020). "S100A8 or S100A9 strongly induced the apoptosis of EoL-1 cells in a time- and dose-dependent manner but had little effect on other leukemia cells." (PMID 32903598, 2020). "We further examined the effects of vildagliptin and its major metabolite M20.7 on the mRNA expression levels of S100A8 and S100A9 in human hepatoma HepG2 and leukemia HL-60 cells." (PMID 27759084, 2016). "One of the important arguments used to support a committed progenitor as the leukemic cell of origin has been the successful generation of leukemia using CTSG, Ctsg, and S100A8 loci, which were thought to target PML-RARA to the promyelocyte compartment." (PMID 23056333, 2012). "As we have shown that JQ1 suppresses S100A8 and S100A9 expression and S100A8 has been shown to promote chemoresistance in leukemia cells, we hypothesised that JQ1 may enhance the effects of drug action in AML cells." (PMID 29955397, 2018). "Indeed, S100A8 serum levels were increased in sera from CRMO patients when compared to healthy controls and individuals with leukemia." (PMID 29250517, 2017). "Finally, we detected the expression of marker genes of macrophage and NK cells, and found that five genes of FCAR, FCGR3A, PREX1, S100A8 and S100A9 all were significantly overexpressed in the leukemia cells of HAP1 compared with that in the normal stroma cells of HS-5 (p < 0.05)." (PMID 39583114, 2024). "In contrast, in the absence of chemo agents, S100A8 and S100A9 can improve HMs by inducing leukemia cell differentiation and apoptosis." (PMID 37686186, 2023). "Therefore, it is not meaningless to hypothesize that preventive action on S100A8 and/or S100A9 levels or expression should help to down modulate the clonal evolution and to prevent leukemia emergence." (PMID 33801279, 2021).
coronary artery disease (23 papers, 2009 to 2026). "A study with a median follow-up of 16.2 years has shown that circulating S100A8/A9 levels could effectively predict the future risk of the events of coronary artery disease and cardiovascular death in a healthy female population." (PMID 33282877, 2020). "The demonstrated associations between S100A8/A9 and the incidence of acute CV events have prompted further research into the role of S100A8/A9 as potential disease mediator and prognostic biomarker in coronary artery disease." (PMID 24453429, 2013). "The circulating S100A8/A9 concentration was positively correlated with traditional cardiovascular risk factors and circulating S100A8/A9 levels could effectively predict the future risk of the events of coronary artery disease and cardiovascular death." (PMID 33282877, 2020). "A correlation between serum S100A8/A9 and fibrinogen levels has already been shown in patients with systemic inflammation in coronary disease." (PMID 38672106, 2024). "The S100A8/9 complex is emerging as a novel biomarker to distinguish patients with acute coronary syndrome from those with stable coronary heart disease." (PMID 37217870, 2023). "It was shown that the expression of S100A8/A9 was high in human atherosclerotic lesions and the blood levels were also increased in the patients with coronary artery diseases (CAD), which implied S100A8/A9 might act as a biomarker for cardiovascular events." (PMID 29379499, 2017). "As biomarker, S100A8/A9 correlates with the extent of subclinical carotid and coronary artery disease, increases rapidly in plasma during myocardial ischemia and necrosis, and is associated with unfavorable prognosis in MI and heart failure patients and in patients undergoing carotid arterectomy." (PMID 24453429, 2013). "Plasma S100A8/A9 complex has been identified as an early and sensitive biomarker that may discriminate between patients with an acute coronary syndrome and those with stable coronary heart disease." (PMID 31534454, 2019). "Elevated systemic levels of the pro-inflammatory alarmin S100A8/A9 correlate with poor prognosis in coronary artery disease (CAD) patients." (PMID 29235502, 2017).
co-infection (19 papers, 2008 to 2025). "Our multicohort analysis established an NB-based diagnostic model utilizing S100A12/S100A8, which maintains diagnostic accuracy across diverse geographic, ethnic, and clinical variables (including HIV co-infection), highlighting its potential for clinical translation in LTBI/ATB differentiation." (PMID 40415930, 2025). "In line with this notion, we observed elevated expression of genes related to pro‐inflammatory responses and neutrophil‐mediated immunopathology (e.g. S100A8/A9/A12) in T cells from patients with severe coinfection, further supporting a role for these cells in disease pathogenesis." (PMID 41163794, 2025).
Hyperglycemia (19 papers, 2013 to 2025). An increased concentration of glucose in the blood. "In streptozotocin-induced diabetic mouse models, hyperglycemia drives bone marrow hematopoiesis by upregulating S100A8/A9, leading to an increase in circulating neutrophils and Ly6-C(hi) monocytes, thereby accelerating AS progression." (PMID 40438395, 2025). "Hyperglycemia induces the production ROS in human endothelial cells with increased endothelial permeability in animal models, with the overexpression of S100A8 and RAGE." (PMID 41155408, 2025). "Hyperglycemia can increase the release of S100A8/S100A9 from neutrophils, and this protein complex interacts with the receptor for advanced glycation end products on myeloid progenitor cells and enhance myelopoiesis." (PMID 34250033, 2021). "Similar to the effects of hyperglycemia on bone marrow, obese adipose tissue releases S100A8/S100A9 and stimulates IL-1β secretion from bone marrow progenitor cells via activation of TLR4/MyD88 signaling and NLRP3 inflammasomes, promoting the expansion of monocytes and neutrophils." (PMID 40438395, 2025). "Furthermore, chronic hyperglycaemia initiates the secretion of a damage-related S100A8 molecule (calgranulin A) from pancreatic islets that in turn increase macrophage infiltration leading to the production of pro-inflammatory cytokines, including IL-1β." (PMID 38962295, 2024). "In addition to promoting monocytosis, hyperglycemia-induced S100A8/A9 also results in increased production of highly reactive platelets (through an independent mechanism), which together results in increased platelet–leukocyte interactions." (PMID 31249530, 2019). "Hyperglycemia induces the production of reactive oxygen species (ROS) in human endothelial cells in vitro and in aortic endothelial cells of diabetic mice in vivo, leading to overexpression of S100A8 and RAGE." (PMID 24453429, 2013). "Similarly, hyperglycemia-induced expression of ROS in neutrophils leads to increased S100A8/A9 secretion." (PMID 24453429, 2013). "Similarly, increased S100A8/A9 secretion in neutrophils could be induced by hyperglycemia." (PMID 41155408, 2025). "In response to hyperglycemia, AGER is activated by S100A8/A9 on hepatic Kupffer cells, leading to the secretion of IL-6." (PMID 35330392, 2022). "Although predominantly expressed in immune cells, expression of S100A8 and S100A9 is increased in activated endothelial cells under conditions of oxidative stress, hyperglycemia, and pro-inflammatory stimuli." (PMID 33679877, 2021). "Recent studies have described that hyperglycemia increases RAGE, S100A8 and HMGB1 expression in aortic endothelial cells, both in vitro and in vivo." (PMID 28099448, 2017). "Indeed, we have previously shown that blocking S100A8/A9 signaling, using a small molecular inhibitor ABR-215757 (Paquinimod), in STZ-diabetic mice prevents hyperglycemia-induced atherogenesis and reduces plaque macrophage content." (PMID 31249530, 2019). "The highest effect of hyperglycemia was gene expression of S100A9 and S100A12, in particular in pro-inflammatory M1 macrophages which are maturated with MCSF and simultaneously stimulated with IFNγ, and for S100A8 in M0 macrophages, maturated without additional stimulation." (PMID 32582175, 2020).